TNF (tumor necrosis factor)
Diseases named in the same sentence as TNF in open-access papers (continued):
Sharing a sentence is not in itself a finding about the gene and the disease.
cancer (continued). "N-3 PUFAs are beneficial as a dietary supplement for cancer patients as they reduce the level of inflammatory cytokines, including IL-2, IL-6, as well as TNF-α, and promote anti-inflammatory activities." (PMID 28410575, 2017). "The examination of inflammatory mediators of cancer cachexia will be delimited to interleukin 6 (IL-6), tumor necrosis factor α (TNF-α), and transforming growth factor β (TGF-β) superfamilies' role." (PMID 28785374, 2017). "Immune cells lyse cancer cells via perforin/granzyme, Fas ligand, tumor necrosis factor (TNF)-α, and TNF-related apoptosis-inducing ligand (TRAIL)." (PMID 28476028, 2017). "The methanol extracts of HD can suppress cancer cell proliferation and induce apoptosis, which involve many tumor-related genes and proteins (e.g. TNF-α, IL-1, NF-κB, Fas, AP-1, Bcl-2, Bcl-xL)." (PMID 28702078, 2017). "Most of these pathways were associated with cancers such as “PI3K-Akt signaling pathway”, “Axon guidance” and “TNF signaling pathway”." (PMID 28881636, 2017). "These inhibitory effects on IAP proteins by SMAC mimetics leads to TNFα-triggered activation of caspase-8 and caspas-3 cascade and thus inducing apoptosis in cancer cells which secrete TNFα in an autocrine fashion." (PMID 28460471, 2017). "The maintenance of an inflammatory TME is further stabilized through the JAK/STAT and the IKK/NF- χβ pathways, whose effects are robustly sustained by a feedback from cancer cells through the production of inflammatory cytokines such as IL-1β, IL-6 and TNF-α." (PMID 28969664, 2017). "Trichodimerol was isolated from P. chrysogenum and inhibits production of TNF-alpha by macrophages and exhibits strong cytotoxic activity on three cancer cell lines." (PMID 28809958, 2017). "TNFR2 expression has been shown to be induced by either TNF or TNF in combination with IL-6 in cancer cell lines." (PMID 29163543, 2017). "Recent published reports indicate that the pro-tumoral activities of TNFα and TGFβ1 are manifested through their impact on the cancer cells and on cells of the TME, such as MSCs that populate the tumors." (PMID 28553282, 2017). "SSd suppresses TNF-α-induced NF-κB activation and its target genes expression to inhibit cancer cell proliferation, invasion, angiogenesis and survival." (PMID 27951737, 2017). "In particular, tumor necrosis factor (TNF) alpha signaling seems to be closely related to cancer-related fatigue." (PMID 28679410, 2017). "Metformin treated cancer cells increased macrophage expression of M1-related cytokines IL-12 and TNF-α and attenuated M2-related cytokines IL-8, IL-10, and TGF-β expression." (PMID 28157701, 2017). "The most highly up-regulated miRNA following IFN-γ and TNF-α treatment in HDLECs was miR-155, which has a central role in the immune system and cancer." (PMID 29066622, 2017). "TNF-α is also considered to be a very important connector between inflammation and cancer progression." (PMID 28575042, 2017). "Briefly, TF-fVIIa signaling via PARs augments the production of pro-inflammatory proteins such as tumor necrosis factor-α (TNF-α), interleukins, and adhesion molecules in cancer cells." (PMID 28417928, 2017). "We next characterize the effect of GEN on cell invasion in HT-29 cells by transwell chamber assay with TNF-α treatment as a positive control, since TNF-α has been proved by several research can induce EMT of kinds of cancer cells." (PMID 29202800, 2017). "The activation of these receptors promotes an increase in the synthesis and release of pro-inflammatory cytokines (TNF-α and IL-6), collaborating to the development of systemic inflammation existing in cancer cachexia." (PMID 29376055, 2017). "Cancer cells resistant to chemotherapy and oncoprotein-targeted drugs display increased IL-1α, IL-6, IL-8, TNF-α, HGF, EGF, VEGF, GM-CSF and SDF-1α expression." (PMID 28928376, 2017).
cancer (continued). "TNF-α in known to promote cell death and apoptosis in a variety of inflammatory conditions including cancer and neurodegenerative diseases, however, its cytoprotective effects has also been shown in other studies." (PMID 28323882, 2017). "Tumor necrosis factor-α (TNF-α) has been considered stimulated the EMT in several kinds of cancer cells which is a function that contrasts with its more established role in inducing apoptosis." (PMID 29202800, 2017). "Cancer screening is arguably particularly important for patients on anti-TNF medications, stopping these medications early should cancer develop potentially improving patient outcome." (PMID 28526972, 2017). "Factors have been described that are able to modulate PON1 gene expression such as some interleukins and tumor necrosis factor-α, explaining the anti-inflammatory effects induced by the enzyme in some disease contexts including cancer." (PMID 28467805, 2017). "Macrophages produce TNF, which activates nuclear factor NF-κB in cancer cells, triggering the production of proteins that stop apoptosis and activate cell proliferation." (PMID 28075340, 2017). "We demonstrated that MUC4 induced by TNFα is able to shield trastuzumab epitope on the HER2 molecule and constitutes a mechanism by which TNFα promotes trastuzumab resistance in HER2-positive cancers." (PMID 29281999, 2017). "Our work provides evidence that activation of alternative endogenous auto- or paracrine TNF sources can attenuate dependency on SM-induced TNF release for efficient cancer cell killing." (PMID 28771230, 2017). "Inflammatory cytokines such as TNF-α contribute to decreased albumin production, and albumin levels can be used as a prognostic indicator for cancer." (PMID 27974681, 2017). "Another cancer-related process that involves TNF-α activity is the epithelial-mesenchymal transition (EMT)." (PMID 29202842, 2017). "Activation of macrophages through their TLR2/4 leads to the release of cytokines such as IL-6 and TNF-α to adjacent cancer cells." (PMID 28969049, 2017). "Several earlier studies have demonstrated the effectiveness of the combination of IFN-γ and TNF-α in inducing apoptosis and necrosis in cancer cells." (PMID 29278364, 2017). "For example, TAMs prime NF-κB activation in both stromal and cancer cells by secreting TNF-α, which in turn upregulates Snail expression." (PMID 28955335, 2017). "Cell culture studies suggested that the anticancer synergy between SMC and OV therapies is due to apoptosis of SMC-treated cancer cells, triggered by TNFα secreted during the OV infection." (PMID 28839138, 2017). "Investigations are underway in our laboratory to evaluate the causal relationship between the baseline serum levels of specific TNF cytokines and the adverse cardiac events in cancer patients receiving doxorubicin treatment." (PMID 28300219, 2017). "Specifically, SMC-mediated depletion of the cIAPs converts the TNF-α-mediated survival response into a death pathway in cancer cells." (PMID 28198370, 2017). "Role of TNF in cancer has attracted attention of researchers and there are several documents about its significant role." (PMID 29511485, 2017). "This agrees with other studies that report 50% inhibition of TNFα-induced activation when cancer cells are treated with 27 μM celecoxib." (PMID 29281684, 2017). "Herein, we have evaluated the consequences of blocking the TNFR1-dependent TNF signalling on anti-PD-1 efficacy in experimental cancer." (PMID 29273790, 2017). "A wide variety of pro- and anti-inflammatory mediators regulate immune response, among them interleukin-1β (IL-1β) and tumor necrosis factor-α (TNF-α) are potent pro-inflammatory cytokines involved in both cancer development and progression." (PMID 28117391, 2017). "Further analysis showed that the upregulated genes are involved in cell adhesion or cancer development, such as NF-κB and TNF signaling pathways." (PMID 29156803, 2017).
cancer (continued). "Many previously published studies have revealed that n-3 PUFAs can down-regulate the levels of IL-6 and TNF-α in cancer patients postoperatively." (PMID 28410575, 2017). "Noteworthy, chemotherapy-induced cognitive impairment, a common sequelae of cancer therapy, has been suggested to result from increased inflammatory mediators such as TNF-α." (PMID 29202842, 2017). "Cancer patients reporting increased social activities and social satisfaction display enhanced stimulated TNF responses, and this cytokine is sensitive to social stressors." (PMID 28753980, 2017). "Mangiferin protects against different human cancers, including lung, colon, breast, and neuronal cancers, through the suppression of tumor necrosis factor α expression, inducible nitric oxide synthase potential, and proliferation and induction of apoptosis." (PMID 28464819, 2017). "Tumor necrosis factor (TNF) is one of the most important factors in the pathogenesis of this cancer." (PMID 29118938, 2017). "Here, we provide evidence that TNF is unlikely a key cytotoxic molecule in three murine cancer models upon anti-PD-1 therapy but rather compromises CD8+ TIL survival." (PMID 29273790, 2017). "This is particularly important in the context of increasing cancer prevalence with more people taking immunosuppressive therapies and broader use of anti-tumor necrosis factor (TNF) monoclonal antibodies such as rituximab for rheumatologic conditions." (PMID 28412974, 2017). "These pathways play important roles in cellular function, and they can be activated and regulated to well-defined signaling molecules such as proinflammatory TNFα and cancer promoting reagent PMA, respectively." (PMID 28592991, 2017). "Although our findings suggest that TNF-α is a potent activator of Wnt signaling, work from other groups showed that there are potential paradoxical roles of TNF-α in terms of the development of cancer." (PMID 28402277, 2017). "Infliximab, anti-TNFα monoclonal antibody, was applied to treat cancer-related cachexia in subjects with pancreatic cancer in clinical phase II." (PMID 29311924, 2017). "If a small fraction of circulating drug reaches cells within tumors, then the low nM concentrations of taxanes required for TNF-α induction are likely clinically relevant for cancer patient tumors." (PMID 28915246, 2017). "The great significance of using the clinical potentials of As2O3 is that it can “kill two birds with one stone” by inhibiting TNF-α to improve RA and possible RA-cancer comorbidity." (PMID 29088724, 2017). "Future extended, long-term studies are required to elucidate the effects of use of medication including thiopurines and TNF-α inhibitors on cancer development." (PMID 29287101, 2017). "TNF-α is able to promote the development of cancer through activating cancer-related pathways or up-regulating Noxo1 and Gna14." (PMID 28938560, 2017). "In vitro phagocytosis assays demonstrated that blocking the TNF pathway with infliximab increases phagocytosis of the cancer cells, and the effect is greater if infliximab is combined with an anti-CD47 blocking antibody (clone Hu5F9-G4)." (PMID 28378740, 2017). "Tumor necrosis factor-α (TNFα) is a key cytokine for building a complex link between inflammation and cancer." (PMID 29109804, 2017). "On the other hand, cytokines like IFN-γ and TNFα are known to regulate cancer cell apoptosis and tumor regression." (PMID 29212184, 2017). "TNF-α, in particular, has established roles in cancer progression in bowel, liver, breast and other sites in mice as well as mammary carcinomata in humans." (PMID 28238104, 2017). "IL-6, TNF-α, and TGF-β are cytokines that have been mechanistically linked to skeletal muscle wasting and disrupted metabolic homeostasis during cancer cachexia." (PMID 28785374, 2017). "TNF-alpha interacts with cancer cells via its specific receptor; this results in activation of arachidonic acid cascade, enhanced generation of reactive oxygen species inside the cell and its death." (PMID 28376925, 2017).
cancer (continued). "Previous study has shown that Nodal, a member of TGF-β family, strengthens both the stability and transcription of Snail and induce EMT in cancer cells, while TNF-α enhances the stability, respectively." (PMID 27057280, 2016). "One possibility is this minor population of target cell death is triggered by cytokine(s) secreted by NK cells upon recognition of the cancer target, such as TNF-α and Interferon-γ." (PMID 27323411, 2016). "The author found that the stem extract was more effective in modulating the response of WEHI-164 cancer cells towards TNFα treatment, and made the cells more sensitive to cell lysis due to TNFα." (PMID 27548121, 2016). "It is possible to draw a hypothetical line separating the anticancer activity of TNF-α and its influence on cancer progression and metastasis." (PMID 27110571, 2016). "We then performed chromatin immunoprecipitation (ChIP) assays with SW1116 cancer cells incubated with TNF-α (50 ng/ml) or PBS." (PMID 27356745, 2016). "We have reported that cytokines, (especially TNFα) secreted by lal−/− Ly6G+ cells are, at least in part, responsible for mediating stimulatory effects on cancer cells." (PMID 26625314, 2016). "For examples, PEGylated GNPs binding with recombinant human tumor necrosis factor alpha (TNF-α) showed potential use in targeting solid tumors in advanced stage cancer patients." (PMID 27467397, 2016). "Cancer patients exhibit decreased albumin production, in all likelihood mediated by TNFα, as TNFα treatment per se is sufficient to inhibit albumin production in vivo (mice and rabbits), or in isolated hepatocytes in vitro." (PMID 26900952, 2016). "Let us denote by x := (g, p) the differentiated cancer cells, by y := (g, p′) the dedifferentiated cancer cells, by zx the T-cells attacking only cells of type x, and by w the TNF-α proteins." (PMID 27063839, 2016). "miR-146a-5p, reportedly involved in immunity and cancer relevant processes, was one of the most highly differentially expressed miRNAs after TNF-α treatment." (PMID 27324794, 2016). "Our results demonstrated that in the presence of ionizing radiation either RKO or SW1463 cancer cells increased mRNA expression levels of the macrophage pro-inflammatory markers TNF, IL6, CCL2 and CCR7 as well as of the anti-inflammatory marker CCL18." (PMID 27513864, 2016). "In vitro stimulation of cancer cells with TNF and LIGHT (peptide activating both canonical and alternative NF-κB signaling pathway) stimulates ZFP91 expression (in MCF-7 cells for TNF and HeLa cells for LIGHT) in a dose dependant manner." (PMID 27975057, 2016). "Mechanistically, TERT was shown to indirectly associate with promoters of NFκB target genes interleukin (IL)-6, tumor necrosis factor (TNFα) and IL-8, which are critical for inflammation and cancer progression, to increase expression." (PMID 26846696, 2016). "Tumor necrosis factor (TNF)-related apoptosis-inducing ligand (TRAIL) selectively targets cancer cells." (PMID 27626799, 2016). "Proinflammatory cytokines interleukin 1 beta (IL-1β), interleukin 6 (IL-6) and tumor necrosis factor alpha (TNF-α) regulates inflammatory response and play significant role in the development of cancer." (PMID 27034760, 2016). "In fact, increased TNF-α is found in muscle wasting related conditions, such as cancer, heart failure, COPD, and sarcopenia." (PMID 27647951, 2016). "TNFα is a cytokine produced by activated macrophages that has potent anti-cancer activities, and has potential as an anti-cancer treatment." (PMID 27548121, 2016). "The previous study showed that anti-TNF-α antibodies demonstrated promising anti-cancer effects in pre-clinical models of PDAC." (PMID 27835602, 2016). "In several cancer cells, TNF-α has been shown to play an important role in the epithelial mesenchymal transition (EMT)." (PMID 26683365, 2016).
cancer (continued). "Rhodus, on the basis of his research analyzing the concentration of TNF-α in saliva, suggests that this cytokine can be used as a prognostic parameter for cancer." (PMID 27547238, 2016). "Surprisingly, after the stimulation of cells with IL-1β or TNFα, after mitophagy induction or in cancer dependent on KRAS signaling, TBK1 is phosphorylated whereas IRF3 is not." (PMID 27538435, 2016). "MUC1 is produced by inflammatory lung macrophages which subsequently secrete TNFα and promote cancer progression." (PMID 27276704, 2016). "It was reported that TNF-α was a powerful anticancer cytokine to mediate cancer-related inflammation." (PMID 27447564, 2016). "Human cancer tissue microarray analysis indicated that MUC16 expression directly correlates with TNFα and IFNγ staining intensities in certain cancers." (PMID 26918940, 2016). "Similar to plants from the genus Viscum, Scurrula also possesses TNFα activity to strengthen the immune system to combat cancer." (PMID 27548121, 2016). "Cytokines, such as tumour necrosis factor alpha (TNF-α), secreted by inflammatory cells play important roles in cancer-related inflammation." (PMID 27009073, 2016). "Anti-TNF-α antibodies have shown therapeutic benefits on various pre-clinical cancer models including orthotopic PDAC pre-clinical model." (PMID 27835602, 2016). "The binding of CF31 and RXR- α results in inhibition of RXR- α transactivation and induces TNF- α dependent cancer cell apoptosis." (PMID 27152946, 2016). "TNFα levels in the plasma of cancer patients positively correlate with tumor growth and increased metastasis in various malignancies." (PMID 27713151, 2016). "Cancer-induced inflammation releases increased levels of circulating inflammatory cytokines such as interleukin 6 and TNFα, both of which initiate SIR." (PMID 27632196, 2016). "TNF-α is primarily produced by macrophages, but it can also be produced by a variety of other stromal cells, as well as cancer cells themselves." (PMID 27042827, 2016). "Especially, pro-inflammatory cytokines such as IL-18, TNF-α, and IL-6 have a positive role in cancer progression, including cancer cell migration." (PMID 27589563, 2016). "Inflammation is recognized as an enabling characteristic in cancer development and IL-6 is one of several cytokines (IL-1, TNFα, IL-23) found to be essential in inflammatory processes and cancer growth." (PMID 27329584, 2016). "We also found a significant response of TBX15 to TNF-α activation of the NF-κB pathway using five cancer cell lines, and similar results were obtained when NF-κB was activated with PMA/ionomycin." (PMID 27327083, 2016). "In 7, 12-dimethylbenz [α]anthracene/terephthalic acid-induced squamous carcinogenesis mice models, Bregs are a significant cellular source of TNF-α and act as important effector cells for TNF-α-mediated promotion of cancer development." (PMID 27331871, 2016). "It has also been proposed that TNFα and IFNγ synergistically inhibit cancer cell growth because IFNγ increases the expression of TNFα receptors." (PMID 27342639, 2016). "Both Scurrula oortiana and Viscum album stimulate production of TNFα that assists the immune system to fight cancer." (PMID 27548121, 2016). "Visceral adipose tissue can release several cytokines as tumor necrosis factor (TNF-α) and interleukin-6 (IL-6) which are considered to form a link between inflammation and cancer." (PMID 27029038, 2016). "It must be borne in mind that TNF-α is documented to play a double-edged role in tumors: while higher levels are anti-tumoural, lower levels induce cancer, angiogenesis and metastasis." (PMID 27548121, 2016).